CD14 (CD14 molecule)
Diseases named in the same sentence as CD14 in open-access papers (continued):
Sharing a sentence is not in itself a finding about the gene and the disease.
gout (continued). "Studies have observed that a reduction of CD14 expression in gout patients may contribute to gout resolution." (PMID 34925366, 2021). "A recent study, however, suggested an opposite role for CD14 in self-limiting gout flares." (PMID 33926105, 2021). "Furthermore, the proportion of CD14+ cells was inversely correlated with the levels of the MPO-dsDNA complex in the synovial fluid of gout patients." (PMID 33741037, 2021). "In addition, anti-inflammatory features, including CD163 expression and IL-10 production from CD14+ cells, were inhibited in RA patients more prominently compared to those with gout." (PMID 32351318, 2020). "In conclusion, these results suggested that CD14 might play a vital role in the mechanism of spontaneous remission of gout." (PMID 31312662, 2019). "Taken together, these results suggest that CD14 might play an important role in self-remission of gout." (PMID 31312662, 2019). "It has been demonstrated that CD14 plays an important role in self-remission of gout." (PMID 31312662, 2019). "In addition, anti-inflammatory features, including CD163 expression and IL-10 production from CD14+ cells, were significantly higher in patients with gout than in those with RA." (PMID 29056937, 2017). "Further, remarkable MRP8 and MRP14 expression was found in CD14+ monocytes/macrophages in gout." (PMID 29056937, 2017). "Finally, we investigated the phagocytic activity of CD14+ monocytes/macrophages in patients with gout." (PMID 29056937, 2017). "Furthermore, CD14+ monocytes upregulation in pediatric gout may indicate an intensified inflammatory milieu." (PMID 40370447, 2025). "In this study, we demonstrated that CD14 might play an important role in self-remission of gout." (PMID 31312662, 2019). "Indeed, previous study have shown that elevated CCL2 levels in the serum are correlated with increased amounts of circulating CD14+ monocytes in subjects with gout and asymptomatic hyperuricemia, suggesting the possible role of CCL2 in the priming and trafficking of monocytes in gout." (PMID 29056937, 2017). "The upregulation of genes like”IL1B”and”CXCL2”in CD14+ monocytes further supports their involvement in the activation of the NLRP3 inflammasome, a critical pathway in gout pathogenesis." (PMID 40370447, 2025). "This suggested that CD16 on CD14− CD16+ monocytes was a potential and essential mediator that orchestrated the protective role of Bacteroides_faecis against gout." (PMID 39492788, 2024). "The proportion of CD14+ macrophages was significantly and inversely correlated with levels of MPO-dsDNA complex in the synovial fluid of gout patients." (PMID 33741037, 2021). "CD14+ macrophages in the synovial fluid of patients with gout displayed significant uptake of NETs, as evidenced by the significant levels of intracellular SYTOX Green in CD14+CD1c−CD3−CD15−CD56− cells in flow cytometry." (PMID 33741037, 2021). "Subsequently, we analyzed whether CD16 on CD14− CD16+ monocytes mediated the effects between Species-Bacteroides_faecis and gout." (PMID 39492788, 2024). "In our study, we observed no significant pro- or anti-inflammatory responses from CD14+ macrophages in the synovial fluid of gout patients after interaction with the NET complexes." (PMID 33741037, 2021). "The number of CD14+CD3−CD19−CD56− monocytes/macrophages was repressed in the synovial fluid mononuclear cells (SFMCs) of RA patients compared to those of gout patients." (PMID 32351318, 2020). "Previous study showed that acute gouty inflammation is triggered by cellular recognition of the naked MSU crystal which was dependent on CD14, and the detection of monocytes and macrophages having ingested MSU crystals is the gold standard clinical procedure to identify gout." (PMID 31312662, 2019). "Further, significantly higher levels of IL-10 were detected with or without stimulation in CD14+ cells from patients with gout compared to those with RA." (PMID 29056937, 2017).
gout (continued). "Therefore, reduced CD14 production in MSU-induced inflammation may contribute to spontaneous remission, and blockade of CD14 function may be useful for refractory gout." (PMID 37734872, 2023). "In addition, the correlations between CD14+ cells, MPO-dsDNA complexes, and expression of pro- and anti-inflammatory cytokines were analyzed in the synovial fluid CD14+ macrophages of patients with gouty arthritis." (PMID 33741037, 2021).
HCMV infection (15 papers, 2012 to 2026). "In the case of human monocyte-derived MΦ CMV infection is associated with a maintained high expression level of CD14 as compared to the decline in mock infection over time of cultivation." (PMID 35203475, 2022). "In contrast, HCMV infection was observed to activate host miRNA expression in CD14+ cells, suggesting a DIDS-insensitive viral function was responsible or, alternatively, that host miRNA expression is a potential anti-viral response to viral internalization." (PMID 42198647, 2026). "The maintenance of CD14 expression during HCMV infection was discussed to fuel their pro-inflammatory response and thus contribute to the pathogenesis of HCMV through induction of inflammation in infected tissues." (PMID 35203475, 2022). "Using an experimental model of latent HCMV infection of CD14+ monocytes, we screened secretomes from three independently generated latent HCMV infections of CD14+ monocytes using antibody arrays." (PMID 33912186, 2021). "We show that CD14+ monocytes are markedly the preferential target of HCMV infection following experimental infection of PBMCs." (PMID 33489936, 2020). "HCMV infection reduced the frequency of B cells while increasing the frequency of CD14+ monocytes within the total human CD45 leukocyte compartment but did not significantly affect the frequency of T cells." (PMID 31431555, 2019). "To address this challenge, we examined HCMV infection by comprehensive analysis of RNA-seq data from diverse human tissues and further used scRNA-seq to analyze gene expression of latently infected CD14+ monocytes and CD34+ HPCs." (PMID 29535194, 2018). "HCMV infection of CD14+ monocytes gives rise to the generation of latency-specific transcripts, conservation of viral genomes, and the capacity of the virus to reenter the lytic cycle." (PMID 28567162, 2017). "The comparison between HCMV-infected and mock-infected macrophages had lead to the observation that HCMV infection maintains CD14, TLR4 and TLR5 surface expression, which declines over time in mock-infected macrophages." (PMID 28567162, 2017). "Human fibroblast and primary CD14+ cells were used as models for lytic and latent HCMV infections, respectively." (PMID 23300789, 2012). "The data presented here suggests that the LUNA protein is an important factor in the reactivation of HCMV infection in CD14+ cells." (PMID 23300789, 2012). "It is well established that HCMV infection extends the lifespan of classically short-lived CD14+ monocytes, which could be important for virus dissemination in vivo." (PMID 37766281, 2023). "In the context of HCMV infection, we have previously demonstrated that secreted factors from latently infected CD34+ cells promoted the migration of CD14+ monocytes and resting CD4+ T cells." (PMID 33912186, 2021). "A similar model applies to the infection of CD14+ cells, whereby MCL-1 upregulation was also demonstrated to be required for the survival of CD14+ monocytes following HCMV infection." (PMID 29547547, 2018). "During latent HCMV infection, virus is known to reside in CD34+ hematopoietic stem cells and derivative CD14+ monocytes." (PMID 28694811, 2017). "Altogether, these results show that β2.7 promotes the silencing of lytic viral genes during HCMV latency in CD14+ monocytes, and in its absence, a portion of monocytes undergo lytic rather than latent HCMV infection." (PMID 36232315, 2022).
metastatic melanoma (15 papers, 2005 to 2026). A melanoma that has spread from its primary site to another anatomic site. "IL2 controlling ITGAM, which in complex with CD14 (both are cell surface markers,), are specific in C10 and this type I cytokine can be associated with durable regression in metastatic melanoma and renal cell carcinoma." (PMID 34238310, 2021). "Herewith, we add enrichment of CD1c+CD14+ myeloid cells in NSCLC patients to the previous observations in peripheral blood of metastatic melanoma and several tumor tissues." (PMID 38242119, 2024). "Our data demonstrated that CD163+ TAMs accumulated in human metastatic melanoma display molecular phenotypes that strongly suggest they are derived from CD14+ CCR2+ monocytes." (PMID 38903497, 2024). "In clinical study, CD14+HLA−DRno/low cells from metastatic melanoma patients showed increased GPNMB expression." (PMID 38140790, 2023). "For instance, BDCA3+ cDC1 and BDCA1+ cDC2 have been identified in the CD16− HLA-DR+ CD11c+ CD14− cell population infiltrating metastatic melanomas, but also in lung, colorectal and breast tumors." (PMID 31366174, 2019). "“HLA DR on CD14− CD16+ monocytes” represents the expression of monocytes in peripheral blood, where CD14+ CD16− HLA DR monocytes have been reported as predictive factors for the response to anti-PD-1 immunotherapy in metastatic melanoma." (PMID 38765682, 2024). "Since the frequency of CD14+CD16−MHCIIhigh monocytes before PD1 ICB treatment was a strong predictor of progression-free and overall survival in patients with metastatic melanoma, the study of monocytes and their differentiation capacity in tumors remain of critical importance." (PMID 32690667, 2020). "Finally, CD14+ BDCA1+ cells, thought to be infDCs, were visualized in skin and colon lesions of metastatic melanoma." (PMID 31366174, 2019). "While CTLA4 expression was not significantly different in CD14+, CD15+, and CD56+ cells between the two groups, the levels were significantly downregulated by approximately 30% in both CD3+ and CD19+ cells from metastatic melanoma patients compared to healthy donors." (PMID 37197667, 2023).
schizophrenia (15 papers, 2013 to 2024). A major psychotic disorder characterized by abnormalities in the perception or expression of reality. "Increased CD14 + levels in serum and cerebrospinal fluid (CSF) have also been associated with schizophrenia and bipolar disorder risk." (PMID 35392269, 2022). "Additionally, the association between CD14 seropositivity and antibodies against C. albicans and gluten with an increased risk of schizophrenia underscores the importance of the interaction between the immune system and the gut microbiota in the pathogenesis of the disease." (PMID 38673018, 2024). "An earlier study also showed downregulated inflammatory genes in CD14+ monocytes isolated from schizophrenia patients compared to bipolar disorder." (PMID 38532012, 2024). "In another recent study, elevated level of soluble CD14 in blood samples drawn from individuals who were subsequently diagnosed with schizophrenia was detected, implicating an advantageous monocytic activation before disease onset." (PMID 38532012, 2024). "Patients with schizophrenia have been observed to have elevated serum antibody levels against fungal pathogens such as S.cerevisiae and Candida albicans, in addition to soluble CD14, a marker of bacterial translocation." (PMID 38673018, 2024). "A previous study revealed that the expression level of CD14 was significantly higher in schizophrenia samples than in controls, indicating an inflammatory state." (PMID 37383091, 2023). "Age of onset negatively correlated with CD14, IL6R, IL1R1, SERPINA3, pan-GFAP and VIM mRNAs in schizophrenia and CD14, IL1B, SERPINA3, pan-GFAP and VIM mRNAs in bipolar disorder." (PMID 34911938, 2021). "In our study, transcript levels of CD16, a marker of natural killer cells and activated macrophages/monocytes, CD163 a marker of perivascular macrophages and CD14, a marker of monocytes were all elevated in schizophrenia cases with high inflammation." (PMID 30214039, 2020). "They found that soluble CD14 was more prevalent in patients with schizophrenia and both sCD14 and LBP correlated with CRP in that group." (PMID 30374300, 2018). "Recent studies found that the soluble form of CD14 (sCD14) was higher in plasma from patients with schizophrenia and bipolar disorder compared with controls." (PMID 28039552, 2017). "Other studies also showed a monocytosis and a high number of CD14+ cells in untreated schizophrenia patients." (PMID 27590010, 2016). "Corroboratively, overexpression of this and other proinflammatory cytokines including IL-6 and tumor necrosis factor (TNF) in isolated CD14+ (classical) monocytes from schizophrenia patients was also found by earlier studies, showing particularly evident in patients with active psychosis." (PMID 38532012, 2024). "Although the role of HLA-DR on CD14- CD16- is rarely mentioned, a recent study still highlights its significant involvement in schizophrenia, warranting further attention." (PMID 38405157, 2024). "In a large and very elegant study, Chen and colleagues further characterized SZ patients’ monocytes and found fewer nonclassically activated monocytes (CD14+/CD16++) in patients with first-episode schizophrenia." (PMID 35337097, 2022). "In contrast to schizophrenia, higher numbers of CD14+ monocytes could not be found in bipolar disorder, yet gene-expression studies identified activation of the circulating cells." (PMID 23506529, 2013).
osteoarthritis (14 papers, 2006 to 2025). A noninflammatory degenerative joint disease occurring chiefly in older persons, characterized by degeneration of the articular cartilage, hypertrophy of bone at the margins and changes in the synovial membrane. "CD3+ T cells are revealed as the predominant immune cells in IFP of dogs with canine cruciate ligament disease, which is associated with osteoarthritis, followed by CD14+ macrophages." (PMID 32189997, 2020). "Freshly isolated cells from muscle from patients with osteoarthritis showed a lower proportion of CD45/CD19/CD14/CD34-negative cells compared to patients with osteoporosis and healthy donors." (PMID 32245507, 2020). "We compared microRNA (miR) expression in CD14+ cells from patients with active RA or with osteoarthritis (OA)." (PMID 26838552, 2016). "In 2006, Bondeson J found that fewer proinflammatory cytokines, such as IL-1 and TNF-α, were produced in digested osteoarthritis synovium cultures after depleting CD14+ cells (CD14 is expressed by classic mononuclear macrophages) using anti-CD14-conjugated magnetic beads." (PMID 37492583, 2023). "Moreover, the complement system components and soluble macrophage biomarkers (CD163 and CD14) are also shown to be upregulated in osteoarthritis." (PMID 32189997, 2020). "By means of anti-CD14-conjugated magnetic beads, specific depletion of osteoarthritis synovial macrophages from these cultures could be achieved." (PMID 17177994, 2006). "Then, the expression of Tyro3TK on CD14+CD16+ and CD14+CD16− monocyte subsets in the peripheral blood of RA, osteoarthritis (OA) patients, and HC were evaluated by flow cytometry and qPCR, and their correlation with RA patient clinical and immunological features was analyzed." (PMID 32958023, 2020). "In addition, we observed that culture of healthy CD209+ DC with IA synovial fluid (SF), but not Osteoarthritis (OA) SF, was sufficient to induce the development of CD209/CD14+ DC, leading to a poly-mature DC phenotype." (PMID 35095831, 2021).
renal cell carcinoma (14 papers, 2013 to 2025). "CD14+ monocytes from peripheral blood in renal cell carcinoma (RCC) cases show remarkable phenotypic changes, which are five times greater than the mean value found in normal subjects." (PMID 37071001, 2023). "This is seen in the setting of renal cell carcinoma, where VISTA is mainly upregulated in APCs (CD14+HLA-DR+ macrophages), and VISTA inhibition was associated with decreased tumor growth." (PMID 36891296, 2023). "B7-H3 and CD14 were co-expressed in renal cell carcinoma tissue, which was positively correlated with an increased tumor burden." (PMID 36829496, 2023). "The effect of PhIP on renal cell carcinoma-mediated osteoclastogenesis on CD14+ monocyte-differentiated osteoclasts was further assessed." (PMID 31569368, 2019). "Recently, two clinical studies have shown that high levels of CD14+HLA-DR−/low and CD11b+CD14−CD15+ MDSCs were negatively associated with survival in renal cell carcinoma patients." (PMID 25436215, 2014). "Similarly, intratumoral and peritumoral accumulation of CD14-positive monocytes prognosticated decreased survival in renal cell carcinoma patients." (PMID 39684692, 2024). "In this study, we detected the presence of the immune markers CD14, CD16, CD56, and CD45 on tumor cells from renal cell carcinoma (RCC) patients." (PMID 40440354, 2025). "Moreover, recent work in clinical renal cell carcinoma samples has shown stable expression of CD45, CD14, CD16, and CD56 on tumor cells in situ, strongly implicating trogocytosis as an active mechanism of membrane acquisition during tumor-immune cell contact in patients." (PMID 41301033, 2025). "In renal cell carcinoma (RCC) patients, the elevated percentage of the T-cell suppressive CD15+ CD14− LDNs among PBMCs declined in response to sunitinib treatment." (PMID 31616408, 2019).